INPP4B (inositol polyphosphate-4-phosphatase type II B)
Diseases named in the same sentence as INPP4B in open-access papers (continued):
Sharing a sentence is not in itself a finding about the gene and the disease.
colon carcinoma (11 papers, 2017 to 2023). "Upregulation of Inositol polyphosphate 4-phosphatase type II (INPP4B) leads to colon cancer cell proliferation, growth, and survival, which is associated with increased activation of PI3K/Akt and SGK3." (PMID 37892232, 2023). "A recent study demonstrated that the increase in INPP4B is due to Ets-1-mediated transcriptional upregulation in colon cancer cells." (PMID 29343273, 2018). "A recent paper has identified that the increased expression of INPP4B is due to transcriptional upregulation mediated by the transcription factor Ets-1 in colon cancer cells." (PMID 29343273, 2018). "In colon cancer cells, INPP4B-mediated degradation of PTEN promoted tumour growth, proliferation and co-operatively enhanced AKT and SGK3 activation downstream of PI3K." (PMID 28082369, 2017). "Nonetheless, INPP4B overexpression promoted anchorage-independent cell growth in FHC colon epithelial cells, cell proliferation in SW620 and HT-29 colon cancer cells, and INPP4B shRNA knockdown in HTC116 colon cancer cells reduced murine xenograft tumour size." (PMID 28082369, 2017). "That is, in colon cancer, INPP4B promotes cell proliferation through SGK3 phosphorylation of AKT." (PMID 36147923, 2022). "INPP4B promotes AML cell growth, and INPP4B silencing inhibits colon cancer cell proliferation and retards colon cancer xenograft growth." (PMID 33879096, 2021). "In contrast, INPP4B acts as an oncogene in AML cells and colon cancer cells." (PMID 33879096, 2021). "Recently, a study has reported that INPP4B dephosphorylates tumor suppressor PTEN through its protein phosphatase activity and subsequent degradation of PTEN, thereby promotes cell proliferation of colon cancer." (PMID 29343273, 2018).
leukemia (10 papers, 2011 to 2024). A malignant (clonal) hematologic disorder, involving hematopoietic stem cells and characterized by the presence of primitive or atypical myeloid or lymphoid cells in the bone marrow and the blood. "This suggests that upregulation of INPP4B/SGK3 was at least partially caused by NPM1-mA expression in leukemia cells." (PMID 29343273, 2018). "We evaluated the potential molecular mechanism underlying INPP4B upregulation in leukemia cells with NPM1-mA." (PMID 29343273, 2018). "Previous reports and the present study suggest that INPP4B provides a survival advantage through the activation of SGK3 in NPM1-mutated leukemia cells." (PMID 29343273, 2018). "As INPP4B protein expression seems largely correlated with its mRNA expression in NPM1-mutated leukemia cells, it is likely that INPP4B is elevated by transcriptional mechanisms." (PMID 29343273, 2018). "To explore the potential mechanisms by which INPP4B contributes to cell proliferation in NPM1-mutated leukemia, we performed siRNA-mediated knockdown of INPP4B in OCI-AML3 cells, and the phosphorylation (activation) of SGK3 and AKT was then monitored." (PMID 29343273, 2018). "In summary, for the first time to our knowledge, our data suggest that overexpression of INPP4B promotes NPM1-mutated leukemia cell proliferation through SGK3 activation." (PMID 29343273, 2018). "In addition, the molecular mechanism underlying INPP4B expression in NPM1-mutated leukemia cells was explored." (PMID 29343273, 2018). "Next, we explored the biological effects of INPP4B overexpression in NPM1-mutated leukemia." (PMID 29343273, 2018). "Thus, in addition to SGK3, the other potential mechanisms underlying oncogenic role of INPP4B in NPM1-mutated leukemia cells needs to be determined." (PMID 29343273, 2018). "The effect of INPP4B knockdown on OCI-AML3 leukemia cell proliferation was evaluated, using the Cell Counting Kit-8 and colony formation assay." (PMID 29343273, 2018). "We thus tested the impact of INPP4B on cellular levels of PI P2 and PI P. The results showed that introduction of exogenous INPP4B decreased PI P2 levels and increased PI P levels in leukemia cells." (PMID 29343273, 2018). "Herein, we report that INPP4B is frequently upregulated in NPM1-mutated AML, and promotes leukemia cell survival in a SGK3-dependent and AKT-independent manner." (PMID 29343273, 2018). "Considering the activation of SGK3 in NPM1-mutated leukemia cells, we assessed the role of SGK3 in INPP4B-mediated cell proliferation." (PMID 29343273, 2018). "Comparison of gene expression profiles in major subgroups revealed that INPP4B expression is increased 12.4 fold in BCR-ABL leukemia compared to all other ALL subgroups." (PMID 21487159, 2011). "Our results indicate that INPP4B promotes leukemia cell survival via SGK3 activation, and INPP4B might be a potential target in the treatment of NPM1-mutated AML." (PMID 29343273, 2018). "Taken together, these findings indicate that INPP4B expression might be upregulated by NPM1-mA via ERK/Ets-1 signaling in leukemia cells." (PMID 29343273, 2018). "Collectively, these findings support the hypothesis that INPP4B activates SGK3 signaling, to promote cell proliferation in NPM1-mutated leukemia." (PMID 29343273, 2018). "Surprisingly, our data demonstrate that loss or gain of INPP4B did not appear to affect AKT activation in NPM1-mutated leukemia cells." (PMID 29343273, 2018). "Considering the fact that INPP4B has protein tyrosine phosphatase activity and Ser/Thr phosphatase activity, whether NPM1 might be a substrate of the INPP4B protein in leukemia remains to be clarified." (PMID 29343273, 2018). "Taken together, our data indicate that INPP4B was, at least in part, required for cell proliferation in OCI-AML3 leukemia cells." (PMID 29343273, 2018). "Given that NPM1-mA enhanced INPP4B expression, we then validated the impact of NPM1-mA on the proliferation of leukemia cells." (PMID 29343273, 2018).
leukemia (continued). "BM-MSCs-Exo directly target the IRF2 gene by secreting miR-222-3p, negatively regulating the IRF2/INPP4B pathway in THP-1 cells, leading to the suppression of leukaemia cell proliferation, the promotion of apoptosis, and the prevention of leukaemia progression." (PMID 39416732, 2024). "This hypothesis was further confirmed, as we found that INPP4B mRNA levels were increased upon ectopic overexpression of NPM1-mA in THP-1 and K562 leukemia cell lines." (PMID 29343273, 2018). "Because AKT is the canonical downstream effector of INPP4B in the PI3K pathway and INPP4B has the seemingly paradoxical role in AKT activation in a variety of different types of cancers, we tested whether INPP4B was involved in the regulation of phosphorylated AKT in leukemia cells." (PMID 29343273, 2018). "For instance, unlike the previous understanding that INPP4B is a negative regulator of PI3K/AKT pathway in TC cells in vivo, the tumor-promoting features of INPP4B have yet been observed in leukemia and BC." (PMID 32333246, 2020).
triple-negative breast carcinoma (10 papers, 2015 to 2025). An invasive breast carcinoma which is negative for expression of estrogen receptor (ER), progesterone receptor (PR), and human epidermal growth factor receptor 2 (HER2). "Loss of heterozygosity (LOH) of the chromosomal region encoding the INPP4B gene (4q31.21) occurs in ∼55% of triple negative breast cancers." (PMID 37471270, 2023). "INPP4B loss, which occurs most frequently in triple-negative breast cancer where PIK3CA mutations are rare, enhances oncogenic PI3K/AKT signaling." (PMID 34035258, 2021). "Another study demonstrated that INPP4B depletion in triple negative breast cancer resulted in delayed EGFR trafficking from early endosomes to late endosomes/lysosomes." (PMID 35760104, 2022). "Moreover, in a genetically-engineered triple-negative breast cancer mouse model INPP4B knockout mice displayed a significant, dose-dependent increase in tumor emergence, indicating a tumor suppressor function of INPP4B in these tumor entities." (PMID 36993823, 2023). "For instance, the expression loss of the negative regulatory proteins PTEN and INPP4B (tumor suppressor genes) in the PI3K-AKT pathway is associated with the occurrence and progression of triple-negative breast cancer, and the loss of PTEN expression is found in more than half of TNBC patients." (PMID 35953532, 2022). "Inositol polyphosphate-4-phosphatase type II B (INPP4B) is another phosphatase that negatively regulates PI3K signaling and has been identified as a tumor suppressor in triple-negative breast cancer." (PMID 41321318, 2025).
colorectal cancer (8 papers, 2017 to 2023). A primary or metastatic malignant neoplasm that affects the colon or rectum. "MiR-1290 could promote the proliferation of colorectal cancer cells via targeting INPP4B." (PMID 35999213, 2022). "Further along this line, primary nonmetastatic colorectal cancer stem-like cells (CR-CSLCs) display significantly reduced INPP4B levels, while they are increased in highly metastatic CR-CSLCs." (PMID 36993823, 2023).
lung carcinoma (8 papers, 2018 to 2025). "Results indicated that 4 proteins, MIG6, CD26, NF2, and INPP4B, were directly linked to the lung cancer subtypes and may be useful in guiding therapeutic decision-making." (PMID 38060494, 2023). "The hematopoietic cell signal transducer HCST, also upregulated in INPP4B overexpressing etoposide resistant Y79 RB cells, has been suggested as a potential biomarker for renal cell carcinoma and lung cancer diagnosis and prognosis." (PMID 36993823, 2023). "We observed that the proteins of MIG6, CD26, NF2 and INPP4B were the direct impact factors for the lung cancer subtypes classification." (PMID 38060494, 2023). "The expression of miR-937 was higher in lung carcinoma tissues than in normal tissues, which can induce the proliferation of lung carcinoma cells through the regulation of INPP4B, whereas the downregulation of miR-937 reduces cell proliferation." (PMID 35290415, 2022). "Our previous genetic screen identified inositol polyphosphate 4-phosphatase type B (INPP4B), primarily hydrolyzing phosphatidylinositol 3, 4-disphosphate, is a potential tumor suppressor in lung cancer cells." (PMID 32341333, 2020). "To further investigate whether INPP4B is upregulated in tumour‐infiltrating T cells, we re‐analysed a single‐cell RNA sequencing (scRNA‐seq) dataset of human lung cancer." (PMID 40754682, 2025). "How INPP4B regulates the genome stability of lung cancer cells is unclear." (PMID 32341333, 2020). "In lung cancer, miR-937 was upregulated and contributed to cell proliferation by inhibiting INPP4B, it might be a valuable target for lung cancer therapy." (PMID 31856857, 2019). "The top 10 proteins (MIG6, GAPDH, NDRG1_pT346, BRD4, CD26, TFRC, INPP4B, GSK3ALPHABETA, IGFBP2, and DUSP4) were screened by applying the WBFS algorithm, and they can be regarded as the candidate biomarkers that are most closely associated with the classification of lung cancer subtypes." (PMID 37509950, 2023). "The study found six promising protein biomarkers that were directly correlated with the classification of lung cancer subtypes, including MIG6, NDRG1_pT346, BRD4, CD26, INPP4B, and DUSP4." (PMID 37509950, 2023).
thyroid cancer (8 papers, 2017 to 2025). "Other reports have shown INPP4B is enriched on early endosomes of thyroid cancer cells, where it suppressed localized AKT2 activation." (PMID 34035258, 2021). "Treatment of thyroid cancer cell lines with 5-Aza-2ʹ-deoxycytidine (5-Aza-CdR), which inhibited DNA methylation, led to INPP4B upregulation." (PMID 29952716, 2018). "Given that INPP4B localises to early endosomes in thyroid cancer cells, these findings provide further evidence of a potential endosomal function for INPP4B in particular cancers." (PMID 28082369, 2017). "For example, depletion of INPP4B selectively activates AKT2 but not AKT1 in the endosomes of thyroid cancer cells." (PMID 30012111, 2018).
hepatocellular carcinoma (5 papers, 2017 to 2023). A malignant tumor that arises from hepatocytes. "For instance, INPP4B was suggested as a direct target of miR-765, through which miR-765 promoted hepatocellular carcinoma cell proliferation and enhanced their tumorigenicity." (PMID 35260141, 2022). "miR-765 promotes cell proliferation by downregulating INPP4B expression in human hepatocellular carcinoma." (PMID 28978114, 2017).
pancreatic cancer (5 papers, 2018 to 2025). "In view of this finding, we sought to characterize the co-expression of INPP4B and Ecad in surgically resected pancreatic cancer tissues if existed, and correlate them respectively with lymph node metastasis status and tumor differentiation grade." (PMID 29952716, 2018). "Meanwhile, PANC-1, started from a human undifferentiated pancreatic carcinoma, was proved relatively minimal in INPP4B level among the four PDAC cell lines we selected." (PMID 29952716, 2018). "A novel 14-gene signature comprising CCDC148, SH3RF2, CACNA1D, POLD3, PARP1, AP1M2, C4orf19, ANO1, VGLL1, SCEL, INPP4B, NET1, INSIG2 and BVES and a corresponding risk score formula were established for pancreatic cancer risk stratification and prognosis prediction." (PMID 33731794, 2021). "By contrast, INPP4B levels were upregulated in gallbladder and pancreatic cancer compared with non-tumor tissues, suggesting an oncogenic role in these tumor entities." (PMID 36993823, 2023).
breast tumors (4 papers, 2015 to 2023). "Interestingly, INPP4B protein expression is frequently lost in primary human PTEN-null breast tumours, and PTEN depletion in mammary epithelial cells phenocopies the changes in cell proliferation, motility and AKT activation following INPP4B depletion." (PMID 28082369, 2017).
cervical cancer (4 papers, 2014 to 2023). A primary or metastatic malignant neoplasm involving the cervix. "Loss of INPP4B protein expression was found in more than 60% of human cervical carcinoma samples." (PMID 29516642, 2018). "It has, however, been shown that in cervical carcinoma cells INPP4B overexpression reduces the phosphorylation of both AKT and SGK3, sharing structural and functional similarities." (PMID 36993823, 2023). "It has been shown that in cervical carcinoma cells INPP4B overexpression reduces the phosphorylation of AKT and SGK3, sharing structural and functional similarities." (PMID 36993823, 2023). "INPP4B impedes the tumorigenic phenotypes of cervical cancer cells by inhibiting the activation of two downstream molecules of the PI3K pathway, AKT and SGK3." (PMID 29516642, 2018). "To understand the mechanisms by which INPP4B reduced the proliferation and invasion of cervical cancer cells, we analysed the expression and activation of several pivotal molecules in the PI3K/AKT pathway." (PMID 29516642, 2018). "We found that overexpression of INPP4B diminished the activity of SGK3 by decreasing its phosphorylation in cervical cancer cells." (PMID 29516642, 2018). "We further explored the role of INPP4B in the migration and invasion ability of cervical cancer cells by Transwell assay." (PMID 29516642, 2018). "In conclusion, INPP4B impedes the proliferation and invasiveness of cervical cancer cells by inhibiting the activation of two downstream molecules of the PI3K pathway, AKT and SGK3." (PMID 29516642, 2018). "We detected INPP4B in normal and cervical cancer tissues by IHC, with normal skeletal muscle tissues as a positive control." (PMID 29516642, 2018). "INPP4B was overexpressed in cervical cancer cells to explore the role of INPP4B in cell proliferation and metastasis." (PMID 29516642, 2018). "In our study, INPP4B expression was lost in the majority of cervical carcinomas, which is consistent with INPP4B as a tumour suppressor." (PMID 29516642, 2018). "As INPP4B inhibits proliferation of cervical cancer in vitro and in vivo, this protein may serve as a possible candidate for adjuvant therapy of cervical cancer." (PMID 29516642, 2018). "INPP4B acts as a tumour suppressor in cervical cancer cells." (PMID 29516642, 2018). "In summary, we have identified INPP4B as a tumour suppressor in cervical cancer." (PMID 29516642, 2018). "In this study, we further assessed the function of INPP4B in cervical cancer." (PMID 29516642, 2018). "To evaluate whether INPP4B suppresses the growth of cervical cancer cells in vivo, we subcutaneously injected HeLa cells stably expressing INPP4B into the armpit of nude mice." (PMID 29516642, 2018). "In this study, we investigated the role of INPP4B in cervical cancer." (PMID 29516642, 2018). "However, the downregulation of INPP4B was only found in 1/9 (11.1%) gastric cancer cell lines and 1/4 (25%) cervical cancer cell lines." (PMID 25126743, 2014). "INPP4B has diverse roles in various tumours, but its role in cervical cancer is largely unknown." (PMID 29516642, 2018). "In addition, INPP4B suppressed tumour growth of xenografted cervical cancer cells in mice." (PMID 29516642, 2018). "In agreement, we found that ectopic expression of INPP4B decreased phospho‐AKT and its downstream molecules in cervical cancer cells." (PMID 29516642, 2018). "Our findings confirmed INPP4B as a tumour suppressor in cervical cancer by regulating AKT and SGK3 activities in various cervical cancer cell lines." (PMID 29516642, 2018).
gastric cancer (4 papers, 2014 to 2023). A primary or metastatic malignant neoplasm involving the stomach. "Moreover, high INPP4B expression has been reported in gastric cancer patients with large tumors and low to undifferentiated metastasis, which is correlated with a poor prognosis." (PMID 36993823, 2023). "As INPP4B levels are significantly decreased in various cancers, it has first been described as a tumor suppressor gene, e.g., in prostate, basal-like breast, ovarian, cervical, gallbladder, and gastric cancer, as well as thyroid neoplasm and multiple myeloma." (PMID 36993823, 2023). "Recently, a similar pattern of results was obtained in gastric cancer (GC) that INPP4B may play dual roles as an oncogene and tumour suppressor gene in different conditions." (PMID 35071242, 2021). "When we tested the basal expression of INPP4B in GC cell lines by western blot, it was found that INPP4B was expressed in all gastric cancer cells but not in normal (GES1) cells, which was consistent with the role of INPP4B as an oncogene in the phenotype experiment of gastric cancer cells." (PMID 34729121, 2021). "Inositol polyphosphate 4-phosphatase type II (INPP4B) negatively regulates PI3K-Akt signalling and plays diverse roles in different types of cancer, but its role in gastric cancer (GC) is still unknown." (PMID 34729121, 2021). "In accordance with our data, INPP4B overexpression promoted SGK3 phosphorylation but did not influence p-AKT levels in AGS gastric cancer cells, while INPP4B reduction elevated AKT phosphorylation, but did not increase p-SGK3 levels in BGC823 gastric cancer cells." (PMID 36993823, 2023).
laryngeal carcinoma (4 papers, 2015 to 2019). Carcinoma that arises from the laryngeal epithelium. "Recently, INPP4B was suggested to be a novel resistance biomarker in human laryngeal cancer, through association of high INPP4B expression levels with resistance to radiotherapy." (PMID 25868852, 2015). "Inhibition of HK-II expression alone did not improve the sensitivity to radiotherapy and chemotherapy in laryngeal carcinoma cells, while co-inhibition of INPP4B and HK-II did." (PMID 31105886, 2019). "After transfection of siRNA against HIF-1α, both hypoxia- and radiation-induced INPP4B expression decreased, indicating that such expression is increased by HIF-1α in laryngeal carcinoma Hep-2 cells." (PMID 27823965, 2017).